INS (insulin)
Diseases named in the same sentence as INS in open-access papers (continued):
Sharing a sentence is not in itself a finding about the gene and the disease.
type 2 diabetes (continued). "Given its central role in protein synthesis and modification, homeostasis of the widely distributed endoplasmic reticulum (ER) is crucial for normal insulin production, with substantial evidence linking ER dysfunction to the aggravation of type 2 diabetes." (PMID 41586316, 2025). "For those with comorbid type 2 diabetes, metformin remains the first-line pharmacologic therapy, improving insulin sensitivity and glycemic control, while GLP-1 receptor agonists are approved for children aged ≥ 10 years." (PMID 41517385, 2025). "Reductions in ER calcium of β-cells have been related to both type 1 and type 2 diabetes, and such calcium dysregulation leads to defects in insulin secretion or synthesis of β-cell." (PMID 40181095, 2025). "Ultimately, one of the most recent studies explored the relationship between SCFAs, specifically butyrate, and their impact on obesity, glucose regulation, and insulin secretion in individuals with metabolic disorders, especially type 2 diabetes and obesity." (PMID 40284169, 2025). "Exercise training has several health benefits in obesity and type 2 diabetes, such as improved insulin sensitivity, cardiorespiratory fitness and body composition, as well as glycaemic management in type 2 diabetes." (PMID 40404819, 2025). "As a nicotinamide derivative, nicotinamide mononucleotide (NMN) can restore NAD+ levels in high-fat diet- or age-induced type 2 diabetic mice, thereby improving their impaired glucose tolerance and enhancing hepatic insulin sensitivity." (PMID 41306436, 2025). "It illustrates a shift from basic research on adipokines and insulin to more systemic and translational topics, including lipid metabolism, gut microbiota, type 2 diabetes, and PCOS." (PMID 40859336, 2025). "Yet, decreased insulin sensitivity and increased insulin secretion have been observed in individuals with type 2 diabetes treated with 10 mg melatonin at bedtime for 3 months." (PMID 40064676, 2025). "Impaired insulin sensitivity and glucose uptake capacity are pathophysiological/phenotypic hallmarks of type 2 diabetes." (PMID 40413649, 2025). "A randomized, double-blind, placebo-controlled clinical trial revealed that EGCG supplementation improved insulin sensitivity, glycemic control, and lipid profiles in individuals with type 2 diabetes." (PMID 39942757, 2025). "If the pancreatic beta cells lost the ability to produce enough insulin, this led to elevated blood glucose levels, and eventually to impaired glucose tolerance and/or type 2 diabetes." (PMID 41009753, 2025). "GLM is a sulfonylurea compound, and sulfonylurea has been widely used as a treatment for type 2 diabetes due to its ability to stimulate insulin secretion from pancreatic β-cells." (PMID 39815341, 2025). "miRNAs are small non-coding RNAs that play a crucial role in post-transcriptional regulation of inflammation, insulin sensitivity, and adipogenesis, processes fundamental in the pathophysiology of type 2 diabetes." (PMID 40076782, 2025). "In mammals, glucagon and insulin are released in a pulsatile manner, which is disrupted in patients with type-2 diabetes, contributing to hyperglucagonemia." (PMID 39747032, 2025). "The largest Type 2 diabetes pregnancy study to date demonstrated evidence of benefit for adding metformin to a standard insulin regimen compared to insulin alone." (PMID 39527377, 2025). "Future studies should also include younger and premenopausal women to clarify vitamin K's role in glucose metabolism, insulin sensitivity, and type 2 diabetes prevention." (PMID 40718363, 2025). "The insulin of the future for both type 1 and type 2 diabetes is probably going to be an insulin analogue that mimics physiological insulin production and is easy to administer in cutting-edge delivery systems." (PMID 40574088, 2025). "Elevated glucose concentration results from insufficient insulin production (Type 1 diabetes) or ineffective insulin utilization (Type 2 diabetes)." (PMID 40067068, 2025).
type 2 diabetes (continued). "This study also found that individuals with type 1 diabetes exhibited lower adherence to insulin therapy when compared to those with type 2 diabetes (aOR = 14.28, C.I 1.34–163.50, p = 0.028)." (PMID 39854487, 2025). "In particular, this holds for type 2 diabetes, because sarcopenia and type 2 diabetes share many etiological and pathogenetic factors, such as insulin resistance, oxidative stress, low-grade chronic inflammation, and adiposity." (PMID 40871710, 2025). "Protein tyrosine phosphatase 1B (PTP1B) is a crucial enzyme involved in regulating insulin and leptin signaling pathways, making it a promising target for treating type 2 diabetes." (PMID 41726330, 2025). "Hypoglycemia can occur in individuals with type 2 diabetes, especially when they are consuming insulin or insulin secretagogues such as sulfonylureas." (PMID 40445127, 2025). "Personalized supplementation with ALA, carnosine, and thiamine significantly reduced glucose in individuals with type 2 diabetes, potentially through increased insulin production." (PMID 40362174, 2025). "Patients with newly diagnosed type 2 diabetes receiving 2–3 weeks of intensive insulin therapy were followed up for at least 1 year in three randomized clinical trials." (PMID 40747755, 2025). "Chromium supplementation has been reported to improve insulin sensitivity and glucose management, particularly in type 2 diabetic populations." (PMID 40573153, 2025). "Efsitora alfa has shown consistent glycaemic control across a broad range of patient populations with type 2 diabetes—from insulin-naïve individuals (QWINT-1, QWINT-2) to those previously treated with basal or basal-bolus insulin (QWINT-3, QWINT-4)." (PMID 40937414, 2025). "A typical MedDiet is rich in fiber used in microbiota to produce short-chain fatty acids, which have been shown to prevent weight gain and to improve insulin sensitivity, albeit mostly in studies with manifested type 2 diabetes." (PMID 41241045, 2025). "Animal experiments have shown that 5‐HT increases serum insulin levels, reduces plasma glucose concentrations, improves glucose tolerance and lipid metabolism in mice with type 2 diabetes, and reduces body weight in a dose‐dependent manner." (PMID 40937192, 2025). "Skeletal muscle comprises ~50% of body mass, and as the primary site for insulin-stimulated glucose disposal, impaired insulin action in this organ often presents early in type 2 diabetes pathogenesis." (PMID 40632859, 2025). "A study revealed that children with mild stunting had higher glucose and insulin levels, reduced beta-cell function, and increased insulin resistance as the main characteristics of type 2 diabetes." (PMID 40362802, 2025). "Using standard [18F]FDG-PET conditions, patients with Type 2 diabetes display different glucose uptake patterns in insulin-sensitive (IS) organs, such as the heart and the brain due to IR." (PMID 40510539, 2025). "This aligns with Hotamisligil’s findings, which explained how inflammation in adipose tissue disrupts insulin signaling, leading to type 2 diabetes and its complications." (PMID 41516014, 2025). "Thiazolidinediones (TZDs) are a class of drugs historically recognized for their role as insulin sensitizers in the treatment of type 2 diabetes." (PMID 40001526, 2025). "Here, we demonstrate that COVID‐19 vaccine boosters impair insulin sensitivity in both mice and patients with type 2 diabetes (T2D)." (PMID 41190280, 2025). "Elevated IL-1β is a hallmark of metabolic inflammation and contributes to both impaired insulin secretion and β-cell apoptosis, thereby accelerating the progression of type 2 diabetes." (PMID 40332318, 2025). "Type 2 diabetes, the most common among adults, is known to occur when the body is resistant to insulin or the body doesn't make enough insulin, which is the hormone that makes the body use sugar and plays a role in regulating the blood sugar levels." (PMID 40650469, 2025).
type 2 diabetes (continued). "When including all measures before and after HIIT, the insulin-mediated suppression of plasma BCAAs was significantly impaired in individuals with type 2 diabetes compared with lean individuals and individuals with obesity (main effect p=0.005)." (PMID 40404819, 2025). "Defects in nutrient-regulated insulin secretion are a key problem in type 2 diabetics; however, how nutrients regulate insulin secretion is incompletely understood." (PMID 40091018, 2025). "This balanced action lowers the risk of hypoglycemia, which is particularly relevant in older adults with type 2 diabetes, where fear of hypoglycemia often hinders timely insulin intensification." (PMID 41293743, 2025). "Moreover, insulin may be associated with an elevated CVD risk in patients with type 2 diabetes." (PMID 40674363, 2025). "Further examination of the influence of social isolation on glucose homeostasis and insulin sensitivity is essential to understanding the potential role of social isolation in the development of type 2 diabetes." (PMID 39821966, 2025). "A potential perceived limitation would be that youth with type 2 diabetes were on diverse treatments, including metformin, insulin, metformin plus insulin, or lifestyle modification." (PMID 40470991, 2025). "Type 2 diabetes was noted in 5% of the sample (n = 5), predominantly controlled with metformin (n = 4) and insulin in one case (n = 1)." (PMID 40142891, 2025). "Reinforcement-learning algorithms for insulin titration in hospitalized type 2 diabetes patients and fully closed-loop systems eliminating mealtime boluses in type 2 adults demonstrate the potential of AI in insulin management." (PMID 41470777, 2025). "This cross‐sectional study included 340 adult participant with type 1 (n = 156) or type 2 diabetes (n = 184) undergoing insulin therapy at the University Hospital Jena." (PMID 40818105, 2025). "Glimepiride is classified as a third-generation sulfonylurea, which is approved by the FDA for the management of type 2 diabetes as a monotherapy and in combination therapy with metformin or insulin." (PMID 40481568, 2025). "We highlight the established role of RyR-mediated CICR in the mechanism of action of common type 2 diabetes treatments, such as glucagon-like peptide-1, which enhances insulin secretion." (PMID 40422193, 2025). "Small pre-meal whey doses have been shown to blunt postprandial hyperglycemia in type 2 diabetes, while in type 1 diabetes, protein-rich meals necessitate individualized insulin adjustments to avoid delayed hyperglycemia." (PMID 41305580, 2025). "Patients with Type 2 diabetes who used sulfonylureas were more prone to experiencing a prolonged QT interval than those who used metformin or insulin." (PMID 41368429, 2025). "Lipids play a central role in the pathogenesis of Type 2 diabetes, as dysregulated lipid metabolism contributes to insulin resistance and metabolic stress." (PMID 40289598, 2025). "This is in contrast to the reported effects of a HPLC diet on lowering plasma glucose and insulin in people with type 2 diabetes." (PMID 40051530, 2025). "In contrast, Type II diabetes involves the body producing insulin that is rendered ineffective due to resistance, leading to high blood sugar levels due to insufficient insulin action or production." (PMID 41383402, 2025). "Type 2 diabetes is a chronic condition where the body becomes resistant to the normal effects of insulin and gradually loses the capacity to produce enough insulin in the pancreas." (PMID 40063948, 2025). "Some factors related to insulin secretion and resistance have been identified; however, only 55% of patients with type 2 diabetes achieve long-term blood glucose treatment goals." (PMID 40296149, 2025). "In a Swedish population study using GADA 250 IU/mL as a cutoff and dividing the patients into high or low, the percentage of patients requiring insulin therapy at 6 months was 42.2% for the high-titer group compared with 3.7% for phenotypic type 2 diabetes." (PMID 40226121, 2025).
type 2 diabetes (continued). "Insulin sensitivity was reduced in individuals with type 2 diabetes compared with individuals with obesity (study I–IV) and lean individuals (studies I and IV), and in individuals with obesity vs lean individuals (study I) (all p<0.05)." (PMID 40404819, 2025). "Type 2 diabetes mellitus (T2DM) is a chronic metabolic disorder characterized by hyperglycemia resulting from impaired insulin action." (PMID 41311766, 2025). "BA men with type 2 diabetes had lower total insulin secretion response to the mixed-meal (p=0.001) and hyperglycaemic clamp (p=0.002), but no ethnic differences were observed in the disposition index within glucose tolerance groups." (PMID 40768046, 2025). "Untreated patients with type 2 diabetes (T2DM) have an increased risk of cancer, likely due to the growth-promoting effects of chronically elevated glucose and insulin levels." (PMID 39796190, 2025). "Hypoglycemia due to increased insulin sensitivity is also reported for human type 2 diabetic patients after treatment with insulin-sensitizing drugs and after gastric bypass surgery." (PMID 41125144, 2025). "Many were insulin dependent prior to liver transplant, which is considered a sign of poorly controlled/advanced type 2 diabetes." (PMID 40664615, 2025). "Resistance exercise training has also been found to have major metabolic health benefits, such as enhanced insulin sensitivity and better glucose management, which are vital for controlling and avoiding type 2 diabetes and other metabolic disorders." (PMID 40760444, 2025). "A validated, self-administered questionnaire was distributed in person to outpatient insulin users with type 1 and type 2 diabetes at King Abdullah University Hospital." (PMID 40471961, 2025). "Infections and failure to adjust insulin therapy to rising glucose levels were also significant precipitating factors in patients with type 2 diabetes." (PMID 40940823, 2025). "There is an unmet need for type 2 diabetes (T2D) treatments for adolescents in addition to metformin and insulin." (PMID 40585887, 2025). "This underscores the observation that even in cases of type 2 diabetes, the proportion of our study cohort’s patients undergoing insulin treatment is higher compared to those in the general practice-based setup." (PMID 39160371, 2025). "Prolonged overwork can lead to β-cell dysfunction, gradually reducing insulin secretion and eventually failing to meet the body’s needs, leading to elevated blood glucose levels and eventually developing into type 2 diabetes." (PMID 39927165, 2025). "Conversely, elevated levels of pro-inflammatory adipokines impair pancreatic β-cell survival and insulin secretion, exacerbating the development of type 2 diabetes." (PMID 40699742, 2025). "Several short-term intervention trials by A. soehngenii L2–7 have shown improvement of insulin sensitivity in prediabetic subjects and type 2 diabetes patients." (PMID 40371708, 2025). "The evaluation of endogenous insulin secretion in type 2 diabetes is important for understanding its pathophysiology, guiding treatment decisions, and predicting patient outcomes." (PMID 40820210, 2025). "Nevertheless, since noninsulin therapies tend to fail overtime because of the progressive decline of insulin secretion, insulin administration becomes a necessity alsofor type 2 diabetes patients." (PMID 40978378, 2025). "Several studies have reported that plasma apoB can predict type 2 diabetes, and plasma apoB has been reported to correlate with total insulin and C‐peptide in obese healthy individuals with a BMI > 27 kg/m2." (PMID 40129271, 2025). "When patients reach the terminal phase of life with unreliable oral intake, oral hypoglycaemic therapy can be withdrawn in patients with type 2 diabetes and once-daily long-acting basal insulin can be given instead." (PMID 40863223, 2025).
type 2 diabetes (continued). "The combination therapy of glucagon‐like peptide‐1 (GLP‐1) RAs with basal insulin provides a more effective glucose management strategy for type 2 diabetes patients, particularly suitable for those requiring stable glucose fluctuations." (PMID 41426511, 2025). "The severe increases in cholesterol, triglycerides, fasting blood glucose, and the reduction in insulin levels support the conclusion that this mouse model effectively represents key aspects of obesity, metabolic syndrome, and Type 2 diabetes." (PMID 40693271, 2025). "In both animal models and humans, elevated inflammatory cytokines have been shown to interrupt the insulin signaling pathway, contributing to insulin resistance and the development of type 2 diabetes." (PMID 40218888, 2025). "Training can improve insulin sensitivity in individuals with type 2 diabetes, but a clear understanding of the mechanisms remains elusive." (PMID 40413649, 2025). "Discontinuation or reduction of sulfonylureas and insulin should occur with careful monitoring by the primary care or provider, as appropriate, for individuals with type 2 diabetes interested in a ketogenic diet." (PMID 40445127, 2025). "Conversely, insulin-resistant states (such as in abdominal obesity or type 2 diabetes) impair muscle protein synthesis and anabolic signaling, hastening muscle atrophy." (PMID 40870469, 2025). "Type-2 diabetes develops as increased insulin levels in the portal vein increase the liver’s sensitivity to growth hormone (GH)." (PMID 41514592, 2025). "The effect of incretins on potentiating insulin secretion is clinically used for the treatment of type 2 diabetes, such as GLP-1 analogues and DPP4 inhibitors which inhibit GLP-1 inactivating enzyme, DPP4." (PMID 40317718, 2025). "Our results suggest that digital twins for Type 2 diabetes are advancing faster in terms of clinical testing, likely due to the larger patient base and less variable insulin dynamics." (PMID 41295206, 2025). "Changes in levels of genes and proteins that mediate insulin signaling, in conjunction with epidemiologic studies, implicate relationships between AD and type 2 diabetes." (PMID 41292426, 2025). "Type 2 diabetes (T2D) occurs when the body becomes resistant to insulin or when the pancreas cannot produce enough insulin to maintain normal blood glucose levels." (PMID 39796627, 2025). "Type 2 diabetes (T2D) is a chronic metabolic disorder characterized by persistent hyperglycemia due to impaired insulin secretion or action." (PMID 41155631, 2025). "Our results remained robust in the sensitivity analysis where insulin prescriptions (ATC code A10A) as a sole indication of type 2 diabetes were omitted." (PMID 40555550, 2025). "As β-cell dysfunction worsens and autoimmune markers emerge, patients with type 2 diabetes become insulin-dependent." (PMID 40225541, 2025). "This agrees with past studies, in which insulin therapy was found to help type 2 diabetes patients manage their health better and stick to their treatment plan." (PMID 40837917, 2025). "Several studies have shown their effect on lowering postprandial glucose and insulin spikes, which makes them useful in the management of type 2 diabetes and metabolic syndrome." (PMID 40870730, 2025). "By deepening our understanding of the molecular pathways governing insulin biosynthesis, we are paving the way for new interventions in the treatment of both type 1 and type 2 diabetes and their long‐term complications." (PMID 40679946, 2025). "This randomized clinical trial of adults with type 2 diabetes assesses the efficacy and safety of an artificial intelligence–based insulin clinical decision support system in achieving glucose control." (PMID 40332936, 2025). "While the therapeutic landscape has expanded with several non-insulin glucose-lowering agents, real-world data show that insulin use remains the cornerstone of treatment for many individuals with type 2 diabetes." (PMID 40937414, 2025).